NLRC4 (NLR family CARD domain containing 4)
Diseases named in the same sentence as NLRC4 in open-access papers (continued):
Sharing a sentence is not in itself a finding about the gene and the disease.
colitis (26 papers, 2013 to 2025). Inflammation of the colon. "In children with the NLRC4 mutation, IL-18BP also ameliorated the severe life-threatening colitis in clinical studies." (PMID 38983847, 2024). "In fact, the deletion of genes encoding NLRC4 or NAIP increased the susceptibility of mice to the development of colitis and CRC associated with colitis." (PMID 39684769, 2024). "In an azoxymethane and dextran sodium sulfate-induced colitis-associated colorectal cancer model, the NLRC4 inflammasome has a protective role in tumorigenesis." (PMID 37077542, 2023). "NLRC4 along with caspase-1 has been shown to regulate tumorigenesis in a mouse model of colitis-associated colorectal cancer (CAC)." (PMID 24273542, 2013). "Mice harboring the NLRC4 T337S mutation exhibit elevated serum IL-18 and canonical inflammasome activation (via Pycard, Casp1, and Gsdmd) in IECs but fail to develop spontaneous colitis or systemic inflammation, even upon immune challenge." (PMID 41116055, 2025). "However, NLRC4-deficient mice manifested intensified colitis induced by DSS compared with wild-type mice." (PMID 33808793, 2021). "Results from these studies show that mice deficient for inflammasome components, including NLRP3, caspase-1, NLRP1, NLRP6, and NLRC4, are highly susceptible to colitis-associated colon cancer induced by AOM/DSS by displaying severe intestinal inflammation, and increased number of colon polyps." (PMID 28955343, 2017). "However, another study using the same chemically induced colitis model shows opposite results, demonstrating an ameliorated severity of colitis in NLRC4-deficient mice." (PMID 24886810, 2014). "Moreover, NLRC4 has been associated with host resistance against a mucosal Candida albicans infection and in a colitis-associated colorectal cancer (CAC) model." (PMID 25071770, 2014). "Together, these findings suggest that adult NLRC4 cKI mice exhibit autoinflammation with mild colitis, serving as a relevant model for adult AIFEC patients." (PMID 41116055, 2025). "All reported cases of NLRC4-mediated colitis have occurred in infancy; among survivors, enterocolitis tends to resolve or attenuate with age, whereas systemic autoinflammation often persists into adolescence or adulthood." (PMID 41116055, 2025). "In the DSS colitis model and DSS-AOM colitis associated colon cancer murine models, several inflammasomes including NLRP3, NLRP6 and NLRC4 have been found to protect against dysplasia and hyperplasia in the colon." (PMID 26378020, 2015). "In a colitis-associated colon cancer model, NLRP3 inflammasome works through myeloid cells whereas NLRC4 inflammasome plays a role in epithelial cells." (PMID 24474192, 2014). "This is suggested by a report that non-pathogenic E. coli strains can be found in the intestinal microflora of mice with DSS-colitis or humans with Crohn’s disease that induce the accumulation of inflammatory macrophages in intestinal tissues via NLRC4 activation." (PMID 41246319, 2025). "Some evidence describes the role of NLRC4 in protecting the gut, since the absence of this sensor caused colonic epithelial injury in DSS-induced colitis mice, whereas another work reported that the severity of colitis was not affected by NLRC4 deficiencies." (PMID 39684769, 2024). "Although deficiency in other inflammasome components, including ASC, caspase-1, and IL-18, also led to dysbiosis and exacerbated colitis, deficiency in NLRC4, NLRP10, NLRP12, and AIM2 had no impact on the susceptibility of WT mice to colitis upon cohousing." (PMID 26925061, 2016). "The differences in microbiota seen in Nlrc4−/− mice did not lead to enhanced susceptibility to DSS-induced colitis." (PMID 24273542, 2013). "Thus, NLRC4 inflammasome-mediated production of IL-1β and IL-18 might be the key factors protecting the host from colonic inflammation and infection." (PMID 33808793, 2021).
colitis (continued). "This aligns with reports of GPR30-mediated NLRP3 inflammasome suppression in cerebral ischemia and colitis models, though our study uniquely implicates IFI16/NLRC4 as key effectors in SAH." (PMID 40726812, 2025). "Using caspase-1/11-/-, NLRP3-/-, NLRC4-/-, IL18-/-, and IL22-/- mice, we showed that KLPJ-mediated colitis occurred through activation of caspase-11, and was dependent on IL18 and partly on IL22." (PMID 36436756, 2023). "LPS, nigericin or ATP stimulated J774A.1 cells and LPS, nigericin, NLRC4 and AIM2 stimulated BMDMs cells in vitro and DSS-induced C57BL/6 mice model of colitis in vivo." (PMID 37367886, 2023). "By contrast, formation of other colitis-relevant inflammasomes such as AIM2, NLRP6, and NLRC4 by DSS was comparable in colons between control and UVRAGFS-expressing mice, highlighting a critical role of the NLRP3 inflammasome in UVRAGFS-associated colitis." (PMID 31831743, 2019). "In an infectious model of colitis with C. rodentium, early activation of the NLRP3 or NLRC4 inflammasomes within the IECs limit pathogen colonization and prevent pathology in mice." (PMID 24886810, 2014). "NLRC4 deficient mice induce more tumors in the AOM/DSS model, but are not related to inflammation and colitis severity in mice is similar to wild-type mice." (PMID 38455052, 2024). "In addition, in a Dextran Sulfate Sodium (DSS)-induced colitis mouse model, DSV and its flagellin enhanced intestinal inflammation and induced significant macrophage pyroptosis, promoting NAIP/NLRC4 inflammasome activation." (PMID 39684769, 2024). "Regulation of the NLRP3 inflammasome using herbal compounds can affect the development of colitis via multiple mechanisms, whereas previous studies have shown that other inflammasome forming NLRs such as NLRP1, NLRP6, NLRC4 and AIM2 are also involved in the pathogenesis of colonic inflammation." (PMID 36090968, 2022). "Like NLRC4, NLRP6 was shown to negatively regulate colitis and CAC in mice." (PMID 24273542, 2013). "Taken together, KLPJ-mediated colitis occurs through caspase-1/11, but not NLRC4 or NLRP3." (PMID 36436756, 2023). "To more specifically evaluate NLRC4V341A effects in a gastrointestinal infection model leading to IL-18 production from IECs, we infected NLRC4V341A/V341A mice with C. rodentium, as NLRC4 responses in non-hematopoietic cells were shown to restrict colitis induced by this enteropathogen." (PMID 38090573, 2023). "In contrast, Nlrc4−/− mice did not exhibit increased colitis and tumorigenesis." (PMID 24474192, 2014). "However, this phenotype was specific to colorectal cancer and not DSS colitis indicating that increased colonic inflammation was not the driving force for the enhanced tumorigenesis seen in Nlrc4−/− and caspase-1−/− mice and instead was likely due to a cell intrinsic mechanism." (PMID 24273542, 2013).
breast cancer (23 papers, 2016 to 2025). A primary or metastatic malignant neoplasm involving the breast. "Previous studies have also shown that NLRC4 is involved in tumor progression, including breast cancer and colitis-associated cancer." (PMID 36457728, 2022). "A previous study revealed that obesity-associated NLRC4 inflammasomes mediated IL-1β release, which promotes the growth of breast cancer by triggering VEGF production and angiogenesis." (PMID 35928454, 2022). "Here we show that obesity-associated NLRC4 inflammasome activation/ interleukin (IL)-1 signalling promotes breast cancer progression." (PMID 27708283, 2016). "The loss of the NLRC4 inflammasome or inhibition of IL-1β is sufficient to abolish the increased tumor progression in obese mice, providing strong evidence that obesity-associated inflammation drives breast cancer progression." (PMID 32630445, 2020). "Importantly, NLRC4 inflammasome activation has been involved in several metabolic diseases such as colitis‐associated tumorigenesis, obesity‐associated breast cancer progression, non‐alcoholic steatohepatitis (NASH), diabetic nephropathy (DN) and type 1 diabetes (T1D)." (PMID 33682108, 2021). "Both pyroptosis-related inflammasomes including NLRP1, NLRP3, NLRC4, AIM2, and the following inflammatory cytokines IL-1β and IL-18 are associated with the immune system in breast cancer." (PMID 36119049, 2022). "Another aspect linking NLRC4 and IL-1β with cancer involves their role in promoting the progression of diet-induced mammary tumors in obese mice." (PMID 34276697, 2021). "For example, NLRC4 mRNA levels is reduced in colorectal cancer compared with normal adjacent tissues but is increased in breast cancer, stomach cancer and glioma." (PMID 34276697, 2021). "Activated NLRC4 leading to IL‐1β signalling has been reported to contribute to pathology and angiogenesis in obese mice with breast cancer via adipocyte‐mediated vascular endothelial growth factor A (VEGFA) expression." (PMID 33682108, 2021). "In particular, P2Y2R activation by ATP released from breast cancer cells induced tumor progression by regulating the inflammasome components NLRC4, ASC, and caspase-1." (PMID 32397236, 2020). "Using syngeneic breast cancer models in mice, we have shown that obesity leads to the NLRC4-inflammasome-mediated activation of IL-1β in infiltrating macrophages, which in turn promotes increased angiogenesis and disease progression." (PMID 32630445, 2020). "And NLRC4 was recently shown to promote mammary tumor growth in a model of high fat diet-induced obesity via the production of IL-1β." (PMID 33042810, 2020). "We next evaluated the relevance of the NLRC4 inflammasome and angiogenesis to breast cancer and obesity in human patients." (PMID 27708283, 2016). "Here, the authors show that obesity promotes breast cancer through the recruitment of macrophages with activated NLRC4 inflammasome, which activate IL-1β production, resulting in VEGFA expression in adipocytes and angiogenesis." (PMID 27708283, 2016). "More and more studies have attested that higher NLRC4 expression in breast cancer and glioma." (PMID 36119049, 2022). "These researches indicate that the high expression and activation of inflammasomes NLRP3, NLRP1, and NLRC4 may promote breast cancer progression including growth, metastasis, and invasion." (PMID 36119049, 2022). "Indeed, studies of both human breast cancer patients and glioma patients have shown a similar relationship between higher NLRC4 expression and poor prognosis." (PMID 34276697, 2021). "In conclusion, in the present study, we demonstrated that P2Y2R, which is activated by ATP secreted from breast cancer cells, regulates inflammasome expression, especially the inflammasome components NLRC4, ASC, and caspase-1, ultimately resulting in increased tumor invasion and angiogenesis." (PMID 32397236, 2020).
breast cancer (continued). "Finally, we confirmed that P2Y2R activation by ATP mediated IL-1β and VEGF-A production and subsequent invasiveness of breast cancer cells through activation of NLRC4, ASC, and caspase-1 of inflammasome components." (PMID 32397236, 2020). "The NLRC4 inflammasome mediates the expression of adipocyte-mediated vascular endothelial growth factor A and angiogenesis, which accelerates the progression of breast cancer." (PMID 32397236, 2020). "Likewise, increased expression of NLRC4 was found in tumor tissues from obese breast cancer patients and NLRC4 inflammasome is required for obesity-driven breast-cancer progression in diet-induced obese mice." (PMID 32155890, 2020). "Obesity-associated NLRC4 inflammasome activation could also mediate the adipocyte-mediated vascular endothelial growth factor A (VEGFA) expression and angiogenesis, which speed up the course of invasion in breast cancer." (PMID 36119049, 2022). "Furthermore, CASP8 (2%), NLRC4 (1%), NLRP3 (1%), NLRP2 (1%), PLCG1 (1%), NLRP1 (1%), NLRP7 (1%), SCAF11 (1%), GSDMC (1%), and NOD1 (1%) occurred somatic mutations as well as most of them had high frequencies of CNV in breast cancer." (PMID 34589498, 2021). "In particular, via controlling innate and adaptive immunity as well as tumor growth, NLRP1, NLRP3, NLRC4, and AIM2 have an effect on how breast cancer develops." (PMID 36119049, 2022). "A previous study discovered that NLRP1, NLRP3, NLRC4, and AIM2 inflammasome complex proteins had pro- or antitumoral properties, especially in breast cancer." (PMID 36437954, 2022). "Moreover, NLRC4, ASC, and caspase-1 protein levels were induced in response to TNF-α or ATP treatment in a P2Y2R-dependent manner, suggesting that the ATP released by TNF-α treatment activates P2Y2R and regulates inflammasome expression in breast cancer cells." (PMID 32397236, 2020). "Notably, a protumorigenic role of NLRC4 coming from the myeloid compartment has been described in mouse models of high-fat diet–induced CRC and breast cancer, although the tumor-intrinsic role of NLRC4 was not investigated." (PMID 38652550, 2024).
glioma (21 papers, 2019 to 2025). A benign or malignant brain and spinal cord tumor that arises from glial cells (astrocytes, oligodendrocytes, ependymal cells). "Recently, progress has been made in studying the function and molecular association of the NLRC4 inflammasome in glioma." (PMID 37723542, 2023). "Tim-3/Gal-9 and NLRC4 inflammasome-related molecule expression levels increased with WHO glioma grade, and this association was correlated with low survival." (PMID 35216164, 2022). "The present study showed that Tim-3/Gal-9 are associated with poor prognosis in glioma patients and induce NLRC4 inflammasome formation and activation." (PMID 35216164, 2022). "NLRC4 expression was associated with a poor prognosis in glioma patients, and the upregulation of NLRC4 in astrocytomas was associated with poor survival." (PMID 31133717, 2019). "Our results suggest that the upregulation of the NLRC4 inflammasome contributes to a poor prognosis for gliomas and presents a potential therapeutic target and diagnostic marker." (PMID 31133717, 2019). "Although astrocytic NLRC4 has been implicated in Alzheimer’s disease and multiple sclerosis, the present report using the TCGA glioma dataset is the first description of NLRC4 expression and its effects on the clinical prognosis in patients with astrocytomas." (PMID 31133717, 2019). "The results of this study reveal that NLRP3 and NLRC4 inflammasomes are expressed and activated in gliomas and that high expression of NLRC4 in particular is associated with poor overall survival." (PMID 31133717, 2019). "Whereas both NLRP3 and NLRC4 were expressed in the brain and colocalized with caspase-1, only NLRC4’s expression was elevated in glioma samples and correlated with poor diagnostic of these patients." (PMID 31892810, 2019). "Here, we investigated whether the upregulation of the NLRC4 inflammasome is associated with the clinical prognosis of gliomas." (PMID 31133717, 2019). "In addition, the protein level of NLRC4 was upregulated and linked with unfavorable prognosis in glioma patients, demonstrating that NLRC4 is a diagnostic biomarker and potential therapeutic target for glioma." (PMID 36920176, 2023). "The inflammatory microenvironment driven by NLRC4 inflammasomes can promote malignancy in various tissues, including prostate and glioma." (PMID 40692785, 2025). "Pyroptosis induced by GSDMD and NLRC4 in high-grade gliomas can promote the progression of gliomas and enhance the sensitivity of these tumors to immune checkpoint therapy by recruiting immune cells." (PMID 38304430, 2024). "In a recent study, inhibition of TIM-3, an immune checkpoint molecule robustly expressed in glioma, was suggested as a therapeutic strategy to inhibit the NLRC4 inflammasome in glioma cells." (PMID 37723542, 2023). "The role of the NLRC4 inflammasome in gliomas was first described in 2019, and our findings identified that robust expression and activation of NLRC4 are associated with glioma progression and prognosis." (PMID 37723542, 2023). "As with other tumors or autoimmune diseases, various inflammasomes, including NLRP3 and NLRC4, have been reported in glioma." (PMID 37723542, 2023). "Both NLRC4 and NLRP3 have been found to be upregulated and associated with poor prognosis in glioma." (PMID 38002346, 2023). "Expression profiles of inflammasomes in glioma support the involvement of NLRC4 in gliomas, and based on this, more specific functional studies have been subsequently conducted." (PMID 37723542, 2023). "The Tim3-Gal-9 axis upregulates the expression and activation of the NLRC4 inflammasome to induce an inflammatory response in glioma." (PMID 37723542, 2023). "The NLRC4 inflammasome and caspase-1 expression levels were dramatically increased in glioma cells transfected with pcDNA harboring Tim-3 or Gal-9." (PMID 35216164, 2022).